SIAH2 (siah E3 ubiquitin protein ligase 2)
Description:
E3 ubiquitin-protein ligase that mediates ubiquitination and subsequent proteasomal degradation of target proteins. E3 ubiquitin ligases accept ubiquitin from an E2 ubiquitin-conjugating enzyme in the form of a thioester and then directly transfers the ubiquitin to targeted substrates. Mediates E3 ubiquitin ligase activity either through direct binding to substrates or by functioning as the essential RING domain subunit of larger E3 complexes. Triggers the ubiquitin-mediated degradation of many substrates, including proteins involved in transcription regulation (GPS2, POU2AF1, PML, NCOR1), a cell surface receptor (DCC), an antiapoptotic protein (BAG1), and a protein involved in synaptic vesicle function in neurons (SYP). Mediates ubiquitination and proteasomal degradation of DYRK2 in response to hypoxia. It is thereby involved in apoptosis, tumor suppression, cell cycle, transcription and signaling processes. Has some overlapping function with SIAH1. Triggers the ubiquitin-mediated degradation of TRAF2, whereas SIAH1 does not. Promotes monoubiquitination of SNCA. Regulates cellular clock function via ubiquitination of the circadian transcriptional repressors NR1D1 and NR1D2 leading to their proteasomal degradation. Plays an important role in mediating the rhythmic degradation/clearance of NR1D1 and NR1D2 contributing to their circadian profile of protein abundance. Mediates ubiquitination and degradation of EGLN2 and EGLN3 in response to the unfolded protein response (UPR), leading to their degradation and subsequent stabilization of ATF4 (By similarity). Also part of the Wnt signaling pathway in which it mediates the Wnt-induced ubiquitin-mediated proteasomal degradation of AXIN1.
Synonyms: hSiah2
Tractability: PROTAC: ubiquitination databases record sites on it.
Gene: Protein-coding gene on chromosome 3 (150,741,125 to 150,763,477, reverse strand). Ensembl gene ENSG00000181788.
Subcellular location: Cytoplasm; Nucleus
Subcellular location (Human Protein Atlas): Nucleoplasm; Vesicles
Pathways (Reactome):
Metabolism of proteins: Amyloid fiber formation; Ub-specific processing proteases
Developmental Biology: Netrin-1 signaling
Immune System: Antigen processing: Ubiquitination & Proteasome degradation
Gene Ontology:
Molecular function: protein binding; transcription corepressor activity; ubiquitin conjugating enzyme binding; ubiquitin protein ligase activity; ubiquitin-protein transferase activity; zinc ion binding
Biological process: canonical Wnt signaling pathway; negative regulation of apoptotic process; negative regulation of canonical Wnt signaling pathway; negative regulation of extrinsic apoptotic signaling pathway; regulation of circadian rhythm; ubiquitin-dependent protein catabolic process; amyloid fibril formation; proteasome-mediated ubiquitin-dependent protein catabolic process; small GTPase-mediated signal transduction; negative regulation of DNA-templated transcription; protein ubiquitination; regulation of apoptotic signaling pathway; regulation of protein ubiquitination
Cellular component: cytoplasm; cytosol; nucleoplasm; nucleus; early endosome; neuronal cell body
Genetic constraint (gnomAD): Loss-of-function variants: 4 observed, 19.9 expected, observed/expected ratio (o/e) 0.2, 90% interval 0.098 to 0.46. The upper end of that interval is the gene's LOEUF score, 0.46, which puts it in group 2 of 6, group 1 being the genes least tolerant of losing a copy. Missense variants: 259 observed, 414.49 expected, observed/expected ratio (o/e) 0.62, 90% interval 0.56 to 0.69. Synonymous variants: 171 observed, 176.27 expected, observed/expected ratio (o/e) 0.97, 90% interval 0.86 to 1.1.
Homologues: Orthologues: chimpanzee SIAH2 (100% identical), macaque SIAH2 (100% identical), rat Siah2 (98% identical), mouse Siah2 (98% identical), dog SIAH2 (97% identical), guinea pig SIAH2 (97% identical), pig SIAH2 (96% identical), tropical clawed frog siah2 (84% identical), zebrafish siah2l (77% identical), Drosophila melanogaster sina (65% identical), rabbit SIAH2 (65% identical). Paralogues in human: SIAH1 (69% identical), SIAH3 (34% identical), ZSWIM9 (20% identical).
Diseases named in the same sentence as SIAH2 in open-access papers:
SIAH2 is named in the same sentence as 66 diseases in open-access papers, as found by Europe PMC text mining. Sharing a sentence is not in itself a finding about the gene and the disease. The quoted sentences say what the papers report.
breast carcinoma (33 papers, 2010 to 2025). "The survival analysis indicated that the higher expression of ARIH1, SIAH1, and UBR5 was associated with shorter OS in breast cancer patients, whereas the higher expression of SIAH2 correlated with prolonged survival." (PMID 40004017, 2025). "In primary breast cancer patients treated with adjuvant tamoxifen, SIAH2 was associated with improved metastasis-free survival (HR = 0.73; p = 0.005)." (PMID 40004017, 2025). "Hypoxia-caused activation of SIAH2/HIF-1α pathway in breast cancer SP cells was also repressed by miR-340-5p mimics." (PMID 35309179, 2022). "It is reported that the expression of SIAH2 in breast cancer is higher than that in healthy breasts, and the high expression of SIAH2 is associated with a decrease in disease-free survival in breast cancer patients." (PMID 35309179, 2022). "Taken together, sinomenine inhibits hypoxia-caused VM formation and metastasis of breast cancer SP cells by regulating the miR-340-5p/SIAH2 axis." (PMID 35309179, 2022). "SIAH2 is an ER-positive epithelial breast cancer subtype gene and is strongly associated with ER levels." (PMID 24244489, 2013). "Recent studies demonstrated that lower expression of Siah2 was associated with resistance to endocrine therapy in breast cancer." (PMID 20682032, 2010). "Indeed, high SIAH2 gene expression was associated with favorable relapse free survival (RFS) among breast cancer patients and, in particular, among patients lacking sufficient expression of ER and HER2 (including TNBCs)." (PMID 39781456, 2025). "Interestingly, SIAH2 is known to be associated with breast cancer risk and cellular response to hypoxia -a phenotype that has been associated with melanoma and pigmentation in general." (PMID 38625909, 2024). "Interestingly, in breast cancer tumors, the expression of SIAH2 increases with tumor grading and this increase in SIAH2 expression is associated with gene copy numbers, again hitting the genetic locus where SIAH2 is located." (PMID 24833526, 2014). "The results indicated that high expression levels of OPN4, NOS2, GPR157, NCOA2, CLOCK, and TH were associated with shorter OS in breast cancer patients, while high expression of EGR3, NR1H3, RELB, SIAH2, and ADRB1 was linked to improved survival rates." (PMID 41031266, 2025). "Hypoxia-induced downregulation of miR-340-5p promotes EMT and metastasis in breast cancer cells by upregulating SIAH2 expression, which directly stabilizes HIF1α expression." (PMID 37583933, 2023). "Hypoxia-driven downregulation of miR-340-5p promotes EMT and metastasis in breast cancer cells by upregulating E3 ubiquitin ligase SIAH2, which directly stabilizes HIF1α." (PMID 37583933, 2023). "With the administration of sinomenine, hypoxia-induced VM formation and metastasis of breast cancer SP cells were reduced, accompanied by the upregulation of miR-340-5p and downregulation of SIAH2." (PMID 35309179, 2022). "This study revealed that sinomenine can repress the VM formation and metastasis of breast cancer SP cells by modulating the miR-340-5p/SIAH2 axis." (PMID 35309179, 2022). "SIAH2, which is closely related to the progression of breast cancer, has been reported to affect the stability of HIF-1α." (PMID 35309179, 2022). "As expected, the inhibition of sinomenine on hypoxia-triggered VM formation and migration of breast cancer SP cells were effectively neutralized by miR-340-5p inhibitor or SIAH2 overexpression." (PMID 35309179, 2022). "MiR-340-5p, which was downregulated in the more aggressive breast cancer cell lines, was confirmed to target and downregulate SIAH2 in this study." (PMID 35309179, 2022).
breast carcinoma (continued). "Taken together, sinomenine can inhibit hypoxia-triggered VM formation and metastasis of breast cancer SP cells by regulating the miR-340-5p/SIAH2 axis." (PMID 35309179, 2022). "Degradation of C/EBPδ mediated by SIAH2 leads to increased cell proliferation, migration, and invasion of breast cancer cells." (PMID 33842469, 2021). "A recent study has linked SIAH2 to the cellular response to oxidative stress, remodeling of the tumor microenvironment, and tumor progression by targeting NRF1 for degradation in breast cancer." (PMID 33842469, 2021). "Mounting evidence supports the role of SIAH2 as a tumor promoter in multiple types of cancer, including melanoma, prostate cancer, pancreatic cancer, breast cancer, gastric cancer, and lung cancer." (PMID 33842469, 2021). "Next, we checked the expression level of NRF1 and SIAH2 in clinical samples and found that NRF1 and SIAH2 were abundant in normal and breast cancer tissues, respectively." (PMID 30833558, 2019). "In ERα-positive breast cancer cells, estrogen stimulates gene expression by upregulating Siah2 transcription and stimulating Siah2-mediated N-CoR degradation." (PMID 30987673, 2019). "Of note, in ER positive breast cancer cells, estrogen can activate ER and induce SIAH2 expression that subsequently ubiquitinates TNK2 and reduces TNK2 expression." (PMID 27902967, 2017). "In another study addressing the role of SIAH1 and SIAH2 in a syngeneic model of breast cancer, the authors observed that blockade of SIAH-substrate binding site resulted in reduced tumor growth and angiogenesis." (PMID 26580787, 2015). "Future fine mapping and functional analysis studies are warranted to investigate the precise role of SIAH2 in the pathogenesis of breast cancer." (PMID 24244489, 2013). "Growing evidence also indicates an important function for SIAH2 in tumor development and progression based on a study of mammary tumors." (PMID 24244489, 2013). "We investigated the frequency and expression pattern of SIAH2 in two independent cohorts of sporadic breast cancers." (PMID 21306611, 2011). "In support of this notion, it has been shown by expression microarrays that downregulated SIAH2 in brain metastasis of breast cancer corresponds with low stromal contamination." (PMID 21306611, 2011). "We observed significant upregulation of SIAH2 in the nucleus in the transition from normal to in situ and invasive carcinomas in breast cancer, supporting the notion of an important role of SIAH2 in breast cancer progression." (PMID 21306611, 2011). "The seven in absentia homolog 2 (SIAH2) protein plays a significant role in the hypoxic response by regulating the abundance of hypoxia-inducible factor-α; however, its role in breast carcinoma is unclear." (PMID 21306611, 2011). "Studies have found that SIAH2 acts as a tumor promoter by targeting key tumor suppressor proteins for degradation, facilitating tumorigenesis in various human malignancies, such as prostate cancer, rectal cancer, breast cancer, and liver cancer, etc.." (PMID 39981438, 2025). "Similarly, miR-340-5p targets Seven in absentia homolog 2 (SIAH2) in hypoxia-treated breast cancer stem-like side-population cells, suppressing EMT and VM." (PMID 41400702, 2025). "SIAH2 destabilizes LATS2 in breast cancer through hypoxia signaling." (PMID 38459604, 2024). "The mechanism of action remains to be determined but could involve ubiquitin-dependent regulations, as described in the breast cancer model in which SIAH2 directs the LATS2 kinase to the proteasome." (PMID 38092743, 2023). "In particular, the expression of SIAH2 in breast cancers was higher than that in normal samples." (PMID 35913115, 2022).
breast carcinoma (continued). "Moreover, both miR-340-5p inhibitor and SIAH2 overexpression partly counteracted the inhibitory effects of sinomenine on hypoxia-triggered VM formation and metastasis of breast cancer SP cells." (PMID 35309179, 2022). "In addition, sinomenine notably elevated the levels of miR-340-5p in breast cancer SP cells exposed to hypoxia and reduced the expression of SIAH2 and HIF-1α." (PMID 35309179, 2022). "In contrast, in breast cancer cells, HIPK2 is degraded during periods of low oxygen via association with the E3 ubiquitin ligase SIAH2; this degradation of HIPK2 is necessary as the protein normally represses the expression of HIF-1α by binding at its promoter." (PMID 35285794, 2022). "SIAH2 may interact with estrogen signaling in breast cancer cells in an analogous manner to AR in prostate cancer cells." (PMID 35789210, 2022). "Sinomenine and miR-340-5p/SIAH2 axis may be the promising candidates for the treatment of breast cancer." (PMID 35309179, 2022). "Therefore, sinomenine can inhibit hypoxia-mediated EMT process of breast cancer SP cells by repressing the SIAH2/HIF-1α axis." (PMID 35309179, 2022). "Genes SIAH2, CDH5 and HS3ST2 were reported to be associated with breast cancer." (PMID 31640538, 2019). "Importantly, the transcriptional level of SIAH2 was found elevated and negatively correlated with the expression of many NEMGs in breast cancer samples." (PMID 30833558, 2019). "rs60538652, on SIAH2, rs2912774 on FGFR2 and rs67129489 near PGAM1P5/NTN4 were more strongly associated with ER+ or PR+ cases, while rs9383936 near ESR1 was more strongly associated with ER− or PR− breast cancers (Pheterogeneity <0.05)." (PMID 30323354, 2018). "Similarly, SIAH2 promotes tumour growth through downregulation of LATS2 in breast cancer cells and SIAH2 knockdown xenograft tumor growth is much suppressed." (PMID 27042197, 2016). "The expression of mRNA encoding SIAH1, but not SIAH2, was also increased under hypoxic conditions in breast cancer cell lines." (PMID 25587023, 2014). "Many studies have shown that SIAH2 is closely related to breast cancer." (PMID 24244489, 2013). "Although none of the SNPs showed an overall association with breast cancer, an analysis of the ER status of the breast cancer patients revealed that the SIAH2 locus (rs6788895; P = 5.73×10−4, odds ratio [OR] = 0.81) is associated with ER-positive breast cancer." (PMID 24244489, 2013). "In this study, we have demonstrated that basal-like breast cancers have an intrinsically elevated SIAH2 level as part of its phenotype that may, partly at least, explain the mechanism underlying high HIF-1α expression in this tumor subtype." (PMID 21306611, 2011). "The finding that SIAH2 was significantly associated with HER2 and basal-like intrinsic breast cancer subtypes, which for basal-like cancers was confirmed in multivariate analysis, is in accord with our previous report of an enhanced hypoxic drive in basal-like cancers." (PMID 21306611, 2011). "We have therefore investigated SIAH2 expression in breast cancer in two independent cohorts." (PMID 21306611, 2011). "Thus, sinomenine and miR-340-5p/SIAH2 axis may the promising target strategies for the management of breast cancer." (PMID 35309179, 2022). "Moreover, SIAH2 is closely related with the ER status of breast cancer." (PMID 24244489, 2013). "Furthermore, Siah2 expression predicated a favourable clinical outcome of breast cancer patients." (PMID 20682032, 2010). "The E3 ligase SIAH2 was identified among the high peptide-spectrum matches (PSMs) and has been reported to regulate LATS2 in breast cancer." (PMID 38459604, 2024). "To further explore the clinical relevance of SIAH2-mediated DBC1 degradation, we analyzed the expression of SIAH2 and DBC1 in breast cancer tissue microarrays of patients." (PMID 35913115, 2022). "Through downregulating SIAH2 and HIF-1α, sinomenine can inhibit epithelial-mesenchymal transition process of breast cancer SP cells." (PMID 35309179, 2022).
breast carcinoma (continued). "Consist with these researches, this study found that the expression of SIAH2 and HIF-1α was enhanced in breast cancer SP cells exposed to hypoxia, along with the increased EMT transformation and VM formation." (PMID 35309179, 2022). "(E) Immunohistochemistry staining analysis of the expression levels of SIAH2 and DBC1 in a series of breast cancer patient tissue microarrays." (PMID 35913115, 2022). "Noteworthy was that a handful of genes from this network had been annotated as TSGs either specifically in relation to breast cancer (GATA3, RERG, and SIAH2) or in other types of cancer (DOC2A and RGS22)." (PMID 32605588, 2020). "Upon tyrosine phosphorylation by Src, Siah2 interacts with CCAAT/enhancer‐binding protein delta (C/EBPδ), a tumor suppressor that is down‐regulated during breast cancer progression, and promotes its poly‐ubiquitination and proteasomal degradation." (PMID 26832397, 2016). "Concordant with this, SIAH2 gene expression was higher in breast cancer tissues than normal tissues, and higher in basal (corresponding to TNBC cells) than luminal breast cancer cells." (PMID 39781456, 2025). "Moreover, transfection of miR-340-5p mimics can significantly inhibited the expression of SIAH2 and HIF-1α in breast cancer SP cells exposed to hypoxia." (PMID 35309179, 2022). "Thus, expression of SIAH2 in DDLPS tumor-associated macrophage and other stromal cells indicates SIAH2 expression may serve as a molecular marker distinguishing between DDLPS and WDLPS as well as a therapeutic target in DDLPS similar to melanoma, prostate, and breast cancer." (PMID 35313831, 2022). "Phosphorylation of SIAH2 by SRC apparently increases its activity toward C/EBPδ without affecting the expression level of SIAH2 in breast cancer cells." (PMID 33842469, 2021). "Although the role of HIF has been documented in breast cancer, there are no data on the expression of SIAH2 in this disease." (PMID 21306611, 2011). "Five normal breast tissues, 60 breast carcinomas and 13 breast cancer cell lines were screened for methylation of SIAH2, but no promoter methylation was detected in these cancer cell lines and samples, as shown by the absence of altered methylation profiles." (PMID 21306611, 2011). "Importantly, DBC1 is negatively correlated with SIAH2 expression levels in human breast tumors, suggesting that the SIAH2–DBC1 axis pathway may play a key role in human breast cancer." (PMID 35913115, 2022). "In addition, the E3 ubiquitin ligase, seven in absentia homolog 2 (SIAH2), was suggested to be involved in posttranslational regulation through the polyubiquitination of CEBPD and downstream degradation via the proteasome in breast cancer cells." (PMID 25591788, 2015). "Having found that SIAH1, but not SIAH2, mRNA increased under hypoxia in breast cancer cell lines, we next investigated whether SIAH1 gene expression is HIF-regulated." (PMID 25587023, 2014). "Unlike with the upregulation of SIAH2 and HIF-1α induced by hypoxia, miR-340-5p was decreased by hypoxia in breast cancer SP cells." (PMID 35309179, 2022). "Analysis of gene expression data from human breast cancers revealed that SIAH1, but not SIAH2, mRNA expression showed a significant positive correlation with the expression of multiple HIF target genes." (PMID 25587023, 2014). "Previously, we reported that the E3 ubiquitin ligase SIAH2 promotes the proteasomal degradation of the mutant receptor tyrosine kinase (TK) FLT3-ITD in leukemic cells and of the non-receptor TK ACK1 in breast cancer cells." (PMID 24833526, 2014).